TET3 (tet methylcytosine dioxygenase 3)
Diseases named in the same sentence as TET3 in open-access papers (continued):
Sharing a sentence is not in itself a finding about the gene and the disease.
fibrosis (4 papers, 2020 to 2025). the formation of excess fibrous connective tissue in an organ or tissue in a reparative or reactive process. "In conclusion, our data demonstrate that TET3 is a pivotal regulator of cardiac fibrosis and can be potentially targeted for the intervention of heart failure." (PMID 40921878, 2025). "TET3 in fibrosis patients has been demonstrated to be higher than in control cases." (PMID 39201990, 2024). "Serum TET3 level in fibrosis cases was significantly higher than that in non-fibrosis and controls, respectively." (PMID 37076545, 2023). "The results showed that serum TET3 levels played no significant role in the diagnosis of chronic hepatitis (the non-fibrotic stage); however, this biomarker could be used to distinguish between fibrosis and cirrhosis." (PMID 37076545, 2023).
lupus (4 papers, 2021 to 2023). "Further, we demonstrated the upregulation of Tet1, Tet2, and Tet3 genes in CD4+ T cells of other two lupus strains, B6/lpr and B6.sle123." (PMID 38153351, 2023). "Furthermore, Tet2/Tet3 DKO mice tend to develop systemic lupus erythematosus (SLE)-like autoimmunity disease; compared with typical SLE mouse models, Tet2/Tet3 DKO mice seem to have relatively mild disease." (PMID 34222235, 2021). "A recent study revealed that TET2 and TET3 are significantly increased in human lupus CD4+ T cells, correlating with increased 5hmc levels at promoter regions and gene activation in human lupus CD4+ T cells." (PMID 34062726, 2021).
myeloid leukemia (4 papers, 2015 to 2022). A clonal proliferation of myeloid cells and their precursors in the bone marrow, peripheral blood, and spleen. "In contrast, a recent study in AML patients showed a positive correlation between TET2 and TET3 and KO of both TET2 and TET3 in hematopoietic precursor cells in mice resulted in an almost complete loss of 5hmC and the emergence of myeloid leukemia." (PMID 36059621, 2022). "Together these data show that acute deletion of Tet3 in a Tet2-deficient context, or concurrent deletion of both Tet2 and Tet3, leads to the rapid cell-autonomous induction of an aggressive, transplantable myeloid leukaemia in mice." (PMID 26607761, 2015). "We show here that Tet2−/− mice acutely deleted for Tet3 displayed a rapid, progressive leukocytosis with neutrophilia, monocytosis, thrombocytopenia and severe anaemia, which developed within a few weeks into a highly aggressive myeloid leukaemia in 100% of the mice." (PMID 26607761, 2015).
myeloproliferative neoplasm (4 papers, 2011 to 2022). A clonal hematopoietic stem cell disorder, characterized by proliferation in the bone marrow of one or more of the myeloid (i.e., granulocytic, erythroid, megakaryocytic, and mast cell) lineages. "However, TET2 was reported to play a regulatory role in myeloproliferative neoplasms and myelodysplastic syndromes in the form of functional deletion mutations, whereas TET1 and TET3 were rarely characterized of functional deletion mutations to function in hematological tumors." (PMID 32014008, 2020).
renal fibrosis (4 papers, 2015 to 2023). A final common manifestation of a wide variety of chronic kidney diseases characterized by glomerulosclerosis and tubulointerstitial fibrosis. "In summary, our studies suggest that Hydralazine ameliorates experimental renal fibrosis through inducing de-methylation of aberrantly methylated Rasal1 (and additional genes as well) by Dnmt1 inhibition and by inducing the endogenous Tet3/Tdg de-methylation pathway." (PMID 25717475, 2015). "In the context of renal fibrosis, hydralazine was observed to downregulate mRNA expression of DNMT1 and induce expression of DNMT3a and Tet3." (PMID 33735324, 2021).
thyroid cancer (4 papers, 2019 to 2024). "Our study identifies a novel carcinogenesis mechanism of thyroid cancer caused by TET3-mediated DNA methylation." (PMID 35755313, 2022). "5-hmC via TET3 can regulate the transcription of genes related to the AMPK pathway, and thus TET3 can promote the proliferation, migration, and invasion of thyroid cancer." (PMID 39201247, 2024). "Previous studies have indicated the potential significance of TET3 in tumor recurrence and metastasis in various types of cancer, including ovarian, endometrial, breast, pancreatic, and thyroid cancer (THCA)." (PMID 37718440, 2023). "Then, we identified TET3 was differentially expressed in thyroid cancers and normal tissues from the TET family." (PMID 35755313, 2022). "We identified TET3 was differentially expressed in thyroid cancers and normal tissues from the TET family." (PMID 35755313, 2022). "TET3 can promote the proliferation, migration, and invasion of thyroid cancer." (PMID 35755313, 2022).
chronic lymphocytic leukemia (3 papers, 2020 to 2023). "Moreover, TET3 mRNA was decreased in chronic lymphocytic leukemia cells compared with healthy B cells." (PMID 32209730, 2020).
chronic myelomonocytic leukemia (3 papers, 2020 to 2021). A myelodysplastic/myeloproliferative neoplasm which is characterized by persistent monocytosis, absence of a Philadelphia chromosome and BCR/ABL fusion gene, fewer than 20 percent blasts in the bone marrow and blood, myelodysplasia, and absence of PDGFRA or PDGFRB rearrangement. "Among the three members of TET family genes (TET1, TET2, and TET3), TET1 chromosome translocation and TET2 mutations have been identified in hematopoietic malignancies such as AML and chronic myelomonocytic leukemia (CMML)." (PMID 34885145, 2021). "TET2 mutations frequently occur in AML, myelodysplastic syndromes (MDS) and chronic myelomonocytic leukemia (CMML), whereas TET1 and TET3 mutations rarely happen." (PMID 32209730, 2020).
esophageal squamous cell carcinoma (3 papers, 2017 to 2022). Esophageal squamous cell carcinoma (ESCC) is a type of esophageal carcinoma (EC) that can affect any part of the esophagus, but is usually located in the upper or middle third. "It was recently reported that TET2 expression is lower in esophageal SCC than in normal epithelium and associated with 5-hmC expression; it was speculated that TET2 is more significant in esophageal SCC development than TET1 and TET3." (PMID 28616099, 2017).
fragile X syndrome (3 papers, 2022 to 2025). A genetic syndrome caused by mutations in the FMR1 gene which is responsible for the expression of the fragile X mental retardation 1 protein.
myelodysplastic syndrome (3 papers, 2020 to 2021). A clonal hematopoietic disorder characterized by dysplasia and ineffective hematopoiesis in one or more of the hematopoietic cell lines. "TET2 mutations are frequent in patients with AML, myelodysplastic syndromes (MDS) and chronic myelocytic leukaemia (CML), while TET1 and TET3 mutations are rare." (PMID 34656178, 2021).
oral cancer (3 papers, 2018 to 2020). "Additionally, our site-specific analysis found that hypermethylation of CpG islands in the TET3 promoter was independently associated with aggressive tumor behavior in oropharyngeal and oral cancers." (PMID 29849955, 2018). "In the multivariate Cox proportional hazards analysis, TET3 methylation in T1 and T2 tumor stages, oropharyngeal cancer, and oral cancer patients exhibited high association with poor survival (hazard ratio: 2.64, P = 0.014; 3.55, P = 0.048; 2.63, P = 0.028, respectively)." (PMID 29849955, 2018). "In patients with oral cancer and a methylated TET3 promoter, the adjusted OR for recurrence was 2.63 (95% CI: 1.11–6.24, P = 0.027)." (PMID 29849955, 2018).
oropharyngeal cancer (3 papers, 2018 to 2020). Carcinoma, predominantly squamous cell, arising from the epithelial cells of the oropharynx. "For patients with oropharyngeal cancers with a methylated TET3 promoter, the OR was 3.55 (95% CI: 1.01–12.44; P = 0.047)." (PMID 29849955, 2018).
Stroke (3 papers, 2022 to 2024). Sudden impairment of blood flow to a part of the brain due to occlusion or rupture of an artery to the brain. "Collectively, the results of these studies demonstrate that the mechanism via which TET3 increases 5hmC under oxidative damage after stroke is also involved in protecting the brain from ischemic damage." (PMID 36142283, 2022). "Furthermore, TET3 knockout mice exhibit increased edema, larger infarct size, and motor deficits after stroke, suggesting that TET3 may confer endogenous protection in the context of ischemic stroke." (PMID 40789569, 2024). "Demethylation by TET1, TET3, and Gadd45b controls the expression of galanin, Ng2, bdnf, fgf-1, RAG, and Bdnf IV in the neurorepair mechanism in stroke." (PMID 36142283, 2022).
Uterine leiomyoma (3 papers, 2016 to 2024). The presence of a leiomyoma of the uterus. "We have also reported TET3 overexpression in human uterine leiomyomas (uterine fibroids)." (PMID 39141428, 2024).
anorexia nervosa (2 papers, 2023 to 2025). A disorder most often seen in adolescent females characterized by a refusal to maintain a minimally normal body weight, an intense fear of gaining weight, a disturbance in body image, and, in postmenarcheal females, the development of amenorrhea. "A previous study confirmed that Bobcat339 can effectively degrade the TET3 protein and lead to increased feeding in a TET3-dependent manner, making it a potential clinical drug candidate for treating anorexia nervosa and stress-related disorders." (PMID 40697650, 2025).
brain tumors (2 papers, 2016 to 2017). "For example, the GBM tumor suppressor gene TET3 is likely downregulated by the delivered exosomal miR-24-3p, known to be up-regulated in brain tumors and validated to target TET3 (Tarbase)." (PMID 29163818, 2017). "Up–regulation of TET3 upon TLX knockdown was also confirmed in PBT003-grafted brain tumours from NSG mice treated with virus expressing TLX shRNA compared with that in tumours from control mice." (PMID 26838672, 2016). "Our DNA microarray analyses have identified several tumour suppressors as candidate downstream targets of TLX and TET3, including BTG2 and PPP2R1B, which were also upregulated upon TLX knockdown in PBT003-grafted brain tumours in NSG mice." (PMID 26838672, 2016).
breast tumor (2 papers, 2024). "Besides, hypoxia can induce the upregulation of TET1 and TET3 in breast tumor–initiating cells (BTIC), which is required to activate TNFα–p38–MAPK signaling that drives breast tumor malignancy." (PMID 38468288, 2024).
endometrial adenocarcinoma (2 papers, 2024). "Studies conducted in vitro revealed that estrogen, either alone on combined with progesterone, can increase TET3 expression in human endometrial epithelial cells (HES) and elevate TET3 protein levels in endometrial adenocarcinoma cell lines (AN3)." (PMID 39201247, 2024).
epilepsy (2 papers, 2023 to 2024). A brain disorder characterized by episodes of abnormally increased neuronal discharge resulting in transient episodes of sensory or motor neurological dysfunction, or psychic dysfunction. "To date, in the literature, only 28 patients are reported with pathogenic variants of the TET3 gene, and only 9 of them have epilepsy." (PMID 39273623, 2024). "In 8 patients, one or more epilepsy genes, GRIN2A, TET3, SCN1A, SCN8A, ADGRV1, DLG4, and SLC12A5, were found, and 12 patients had no genetic mutations." (PMID 38813507, 2023).
heart failure (2 papers, 2025 to 2026). Inability of the heart to pump blood at an adequate rate to meet tissue metabolic requirements. "We investigated how statin therapy relates to TET1, TET2 and TET3 expression in circulating immune cells in heart failure with reduced ejection fraction (HFrEF)." (PMID 42193073, 2026).
Hepatic steatosis (2 papers, 2023 to 2025). Steatosis is a term used to denote lipid accumulation within hepatocytes. "Given the previous finding that TET2 and TET3 liver specific KO promoted fatty liver development in mice, we decided to investigate the role of TET1 in hepatic steatosis." (PMID 40164757, 2025).
hypopharyngeal cancer (2 papers, 2018 to 2019). Carcinoma, predominantly squamous cell, arising from the epithelial cells of the hypopharynx. "TET1 was methylated in 34 (59.6%), TET2 in 5 (8.8%), and TET3 in 15 (26.3%) of the 57 hypopharyngeal cancers examined." (PMID 29849955, 2018).
lymph node metastasis (2 papers, 2022 to 2023). "UALCAN database analyses based on the THCA dataset indicated that patients with lymph node metastasis exhibited higher expressions of TET3 and AHR (P < 0.001)." (PMID 37718440, 2023). "The elevated expression of TET3 was significantly correlated with lymph node metastasis (P = 0.047)." (PMID 36518116, 2022). "Based on the univariate analysis, we selected lymph node metastasis (P = 0.001), TMN staging (P = 0.003), and TET3 expression (P = 0.001) for multivariate analysis." (PMID 36518116, 2022).
Neurodevelopmental delay (2 papers, 2024). "In 2020, pathogenic variants of the TET3 gene were associated with Beck–Fahrner syndrome, which is characterized by neurodevelopmental delay, intellectual and learning disabilities of variable degree, growth abnormalities, hypotonia and seizures." (PMID 39273623, 2024). "Recently, mutations in human Tet3 have been shown to cause neurodevelopmental delays." (PMID 38381741, 2024).
osteonecrosis (2 papers, 2025 to 2026). A none disease characterized by death of bone tissue due to a lack of blood supply. "In a murine steroid-associated osteonecrosis model, NIR-activated paCas13d achieves robust TET3 knockdown, disrupting the TET3-5hmC-PTEN axis that drives glucocorticoid-induced osteocyte apoptosis." (PMID 42010284, 2026).
osteosarcoma (2 papers, 2021). A usually aggressive malignant bone-forming mesenchymal neoplasm, predominantly affecting adolescents and young adults. "Specifically, overexpressed MIR22HG is an lncRNA low-expressed in osteosarcoma, which is associated with the suppressed viability and proliferation and the promoted apoptosis of osteosarcoma cells, the effects of which are associated with the regulation on miR-629-5p/TET3 axis." (PMID 34373436, 2021). "From the present study, it can be confirmed that TET3 is the target gene of miR-629-5p, and TET3 overexpression represses the viability and proliferation and enhances the apoptosis of osteosarcoma cells." (PMID 34373436, 2021). "Then we set out to determine the interaction between miR-629-5p and TET3 on transfected osteosarcoma cells, and the effects of miR-629-5p and TET3 on the expression of TET3." (PMID 34373436, 2021). "Obviously, TET3 abolished the effects of miR-629-5p on the viability of transfected osteosarcoma cells (p < 0.05)." (PMID 34373436, 2021). "According to the results, silent TET3 raised the viability of osteosarcoma cells, whereas the overexpressed TET3 acted conversely (p < 0.01)." (PMID 34373436, 2021). "Moreover, TET3, as a target gene of miR-135b, participated in the recurrence and lung metastasis of osteosarcoma." (PMID 34373436, 2021). "This discovery made us wonder whether the effects of miR-629-5p on osteosarcoma could be achieved by targeting TET3." (PMID 34373436, 2021). "In conclusion, the discoveries in this study unveil the participation of lncRNA MIR22HG in osteosarcoma, and demonstrate that overexpressed MIR22HG represses the viability and proliferation but promotes the apoptosis of osteosarcoma cells via the miR-629-5p/TET3 axis." (PMID 34373436, 2021). "In osteosarcoma, miR-135b promotes cell proliferation and invasion by targeting FOXO142 and stimulates recurrence and lung metastasis by targeting TET3 and multiple negative regulators of the Wnt/β-Catenin, including APC, CK1α, GSK3β, and β-TrCP43." (PMID 33990540, 2021).
renal cell carcinoma (2 papers, 2020 to 2023). "Also, it had been proposed that a high mRNA level of TET3 was an independent predictor of poor outcome in patients with renal cell carcinoma." (PMID 36371552, 2023). "Some studies found that TET3 was highly expressed in renal cell carcinoma and endometrial cancers." (PMID 36371552, 2023).
serous ovarian cancer (2 papers, 2016 to 2019). "The ratio of amplification or mutation is almost the same in either serous ovarian cancer or high-grade serous ovarian cancer about TET3 alone or six genes." (PMID 31656201, 2019). "To address the correlation between TET3 mutation and cancer progression, firstly we analyzed TET3 mutation and CNAs in ovarian serous adenocarcinoma including 627 patients in 2 studies by the cBioPortal tools (ovarian: TCGA, Nature 2011 and TCGA, provisional)." (PMID 31656201, 2019). "The correlation between TET3 expression and clinicopathologic features was analyzed to evaluate its prognostic significance of TET3 in serous ovarian cancer patients." (PMID 31656201, 2019).
Splenomegaly (2 papers, 2019 to 2022). Abnormal increased size of the spleen. "Mice with Treg-specific deletion of Tet2 and Tet3 (Tet2/3fl/flFoxp3Cre mice) display defective Treg function and develop an inflammatory disease characterized by splenomegaly and leukocyte infiltration into tissues." (PMID 31043609, 2019). "Decreased TET2 and TET3 was shown to compromise physiological Treg function in animal experiments in which mice lacking TET2 and TET3 in Treg cells develop inflammatory disease with splenomegaly and leukocyte infiltration into the lung." (PMID 35386689, 2022).
adrenocortical adenomas (1 paper, 2019). "In the present study, we analysed the mechanism of the miR-27a-5p-TET3-SYP signal pathway in adrenocortical adenomas causing CPA dysregulation." (PMID 31352437, 2019). "Investigating the role of the miR-27a-5p-TET3-SYP signalling pathway on adrenocortical adenomas will provide new insight into adrenocortical adenomas, and based on this understanding, future drugs targeting specific genes may be developed to treat CPA." (PMID 31352437, 2019).
age (1 paper, 2025). A temporal measurement of the time period elapsed since an identifiable point in the life cycle of an organism. "Targeting TET3 activity is a potential therapeutic strategy for age‐related cardiovascular diseases." (PMID 40547942, 2025).
Anophthalmia (1 paper, 2021). Absence of the globe or eyeball. "Morpholino knockdown of tet3 in Xenopus resulted in anophthalmia; tet3 depletion leads to misregulation of pax6, rx and six3 expression, suggesting a potential role during eye induction." (PMID 33563331, 2021).
Arthritis (1 paper, 2022). Inflammation of a joint. "K/BxN serum-induced arthritis was induced in Wild-type (WT) and TET3 heterozygous-deficient (TET3+/−) C57BL/6 mice." (PMID 36114544, 2022). "The onset of arthritis was initiated, but its progression was clearly aborted by TET3 haploinsufficiency under these conditions." (PMID 36114544, 2022). "To verify the role of TET3 in RA progression in intact animals, we used a mouse model of RA induced by K/BxN serum transfer, in which the expected progression of RA-like arthritis was observed." (PMID 36114544, 2022). "Histological analysis suggested that TET3 haploinsufficiency attenuates the hallmarks of arthritis progression, including reducing synovial inflammation and FLS proliferation following bone destruction." (PMID 36114544, 2022). "Acute arthritis was induced following K/BxN serum transfer in WT and TET3+/− mice." (PMID 36114544, 2022). "In addition, TET3 haploinsufficiency lowered RA progression in a mouse model of serum-induced arthritis." (PMID 36114544, 2022). "However, the progression of arthritis was clearly aborted in TET3+/−-K/BxN mice." (PMID 36114544, 2022).